MC4R (melanocortin 4 receptor)
Diseases named in the same sentence as MC4R in open-access papers (continued):
Sharing a sentence is not in itself a finding about the gene and the disease.
Obesity (continued). "This research elucidated the MC4R Val103Ile association with obesity-related phenotypes (BMI and HbA1c levels)." (PMID 31947684, 2020). "Two polymorphisms (rs12970134 and rs476828) near the MC4R have also been associated with increased risk of obesity in Europeans and Europeans, respectively." (PMID 32770936, 2020). "Although carriers of these 11 MC4R mutations (N = 182) were overall more likely to have obesity, 15% (N = 28) were of normal weight." (PMID 32692746, 2020). "So far, one other study has examined the impact of MC4R variants on obesity in the full UK Biobank population using genotype data." (PMID 32692746, 2020). "Several population studies have generated similar evidence demonstrating the association of MC4R rs2229616 Val103Ile with protection against obesity and increasing MC4R lipolysis activity and eventual reduction in body weight." (PMID 31947684, 2020). "According to a large meta-analysis of genome-wide association studies (GWAS), a common genetic variant near MC4R (rs17782313) was found as a second association signal following FTO rs9939609 for common obesity." (PMID 32758123, 2020). "For example, T2D-associated variants at the obesity-associated MC4R locus (encoding the melanocortin 4 receptor [MIM: 155541]) were assigned as unclassified in our analyses." (PMID 33186544, 2020). "Given the important role of rs17782313 in regulating MC4R activity, the aim of this study was to evaluate the prevalence of this variant in a Kuwaiti cohort and to determine its role in regulating novel obesity biomarkers, especially DNAJC27." (PMID 32733386, 2020). "Since obesity is an established risk factor of cancer, several studies have examined the association between SNPs near the MC4R gene and cancer risk, but the findings are inconsistent." (PMID 32899047, 2020). "Mutations in the melanocortin 4 receptor (MC4R) represent the commonest cause of severe early onset obesity." (PMID 32692746, 2020). "Pathogenic inactivating MC4R mutations are the most frequent cause of monogenic obesity, a growing medical and socioeconomic problem worldwide." (PMID 32785054, 2020). "We identified 59 known obesity-increasing mutations in MC4R from the Human Gene Mutation Database (HGMD) and Clinvar." (PMID 32692746, 2020). "The first cases of MC4R mutation were identified in 1998 in patients affected by severe obesity and hyperphagia." (PMID 33261141, 2020). "We discovered that the MC4R rs17782313, rs476828 and rs12970134 SNPs and their haplotypes were associated with the risk of obesity in the Chinese Maonan population." (PMID 32770936, 2020). "To date, MC4R gene mutations inactivating the MC4R for signaling (loss of function) are the most frequent monogenic cause of obesity." (PMID 32785054, 2020). "The present study also showed strong associations between the MC4R rs17782313 variant and the obesity-related proteins ghrelin and visfatin." (PMID 32733386, 2020). "MC4R has been associated with key components of appetite, food intake, nutrient absorption, thermogenesis, energy expenditure, insulin secretion, obesity, and lipid metabolism." (PMID 32390949, 2020). "Mutations in MC4R have been identified predominantly in small-scale studies of individuals with obesity." (PMID 32692746, 2020). "A genome-wide association study (GWAS) from 2008 reported that the melanocortin 4 receptor gene (MC4R) was associated with obesity." (PMID 32770936, 2020). "Melanocortin 4 receptor (MC4R) gene mutations are related to approximately 6% of obesity cases, being the most common causes of non-syndromic monogenic obesity." (PMID 33362866, 2020). "Consistently, loss-of-function mutations in MC4R gene cause increased appetite and severe early-onset obesity and some patients can also exhibit hyperinsulinemia and increased linear growth." (PMID 33362866, 2020).
Obesity (continued). "Obesity is also a symptom of melanocortin 4 receptor (MC4R) mutations that impair its ciliary localization in both humans and mice, suggesting that ciliary localization is essential for the functionality of this GPCR receptor." (PMID 33282860, 2020). "Taken together, a low polygenic susceptibility to obesity seems to attenuate the impact of pathogenic mutations in MC4R." (PMID 32692746, 2020). "In humans, the loss of MC4R functionscauses severe obesity, but intensivesearch for therapeutic options of MC obesity correction hasyet not identified an efficient drug." (PMID 33659800, 2020). "In mice research, the MC4R gene is associated with hyperinsulinemia before the onset of extreme obesity." (PMID 32807123, 2020). "More common are mutations in the MC4R gene, which have been shown to cause both dominant and recessive forms of monogenic obesity and are responsible for up to 6% of severe, early-onset obesity cases." (PMID 33233816, 2020). "The most common form of monogenic obesity is caused by mutations in the melanocortin 4 receptor (MC4R) gene, and MRC4 signaling is known to activate DARPP-32." (PMID 31896117, 2020). "More recently, MC4R variants with less severe effects on receptor function have been shown to be major modifiers of obesity risk in the wider human population." (PMID 33233816, 2020). "The MC4R rs17782313 polymorphism has been widely studied and found to be significantly associated with obesity, increased snacking, and hunger." (PMID 32111069, 2020). "Among the overrepresented genes, MC4R was the most frequent (1.51% of patients), similar to reports revealing heterozygous and homozygous mutations in MC4R accounting for 1–6% of severe obesity in humans." (PMID 30926952, 2020). "Mutations in MC4R are the most common in monogenetic obesity, present in more than 5% of childhood obesity." (PMID 32982666, 2020). "Although our studies have tested the correlation of three MC4R SNPs and their haplotypes to the risk of obesity, several other gene-environment interactions still need to be measured." (PMID 32770936, 2020). "MC4R is a suitable candidate gene due to MC4R’s central position in the leptin–melanocortin pathway and given MC4R variants are among the most common cause of monogenic human obesity." (PMID 33233816, 2020). "In WD-fed MC4R KO mice, obesity and systemic insulin resistance are likely induced by the combination of hyperphagia induced by MC4R deficiency and dietary lipids and fructose." (PMID 31990961, 2020). "The MC4R has been reported as a risk gene associated with extreme obesity in adolescence and adulthood." (PMID 33193685, 2020). "Little is known about the correlation between the melanocortin 4 receptor gene (MC4R) single nucleotide polymorphisms (SNPs) and the risk of obesity." (PMID 32770936, 2020). "A large-scale meta-analysis of seven genome-wide association studies (GWAS) in 2008 reported MC4R as the second association signal for common obesity." (PMID 32019489, 2020). "Recently, a genomewide association study (GWAS) identified several single nucleotide polymorphisms (SNPs) of the MC4R gene, associated with high BMI and the risk of the development of obesity." (PMID 33202557, 2020). "Animal-based studies showed that Mc4r-deficient mice developed obesity associated with an increase in linear growth, hyperphagia, hyperinsulinemia, and hyperglycemia." (PMID 33362866, 2020). "Targeted deletion of Mc4r in mice causes maturity-onset obesity associated with hyperphagia, hyperinsulinemia, and hyperglycemia." (PMID 33076233, 2020). "The association with obesity of a common variant near the melanocortin-4 receptor (MC4R) gene (rs17782313) has been indicated in various studies." (PMID 32758123, 2020). "Here, we extend the screening of the MC4R gene in new Brazilian patients with severe obesity to identify other pathogenic variants." (PMID 33362866, 2020).
Obesity (continued). "The MC4R gene (rs17782313 and rs17700633) were related to obesity risk and insulin resistance in two genome-wide association studies." (PMID 32807123, 2020). "Taken together, our results support a potential role of the MC4R rs17782313 variant in hypertension and obesity." (PMID 32733386, 2020). "Mutations in the MC4R gene have been associated with early-onset obesity and severe hyperphagia, causing about 5% of severe obesity in children and adults." (PMID 32982666, 2020). "In the present study, we have identified five MC4R variants in patients with severe obesity, with a total prevalence of 3.7%." (PMID 33362866, 2020). "There is growing evidence that rs17782313, a variant mapped 188 kb downstream of MC4R, is related to high dietary intake and different obesity-related phenotypic traits." (PMID 32758123, 2020). "Severe insulin resistance can occur in the setting of severe obesity syndromes resulting from pathogenic variants in MC4R, POMC, LEP, and LEPR." (PMID 33210059, 2020). "The first MC4R variant related to monogenic obesity was a frameshift mutation (c.631_634delCTCT), identified in two heterozygous patients, a 4-years-old boy and his father with early-onset obesity." (PMID 33362866, 2020). "For example, the GPCR MC4R is haploinsufficient, and rare heterozygous mutations that eliminate or reduce receptor expression are associated with obesity." (PMID 33084570, 2020). "Canine MC4R gene polymorphisms have been identified in several studies, with some attempting to analyse their effects on obesity-related phenotypes." (PMID 33233816, 2020). "The MC4R rs17782313 variant is located 188 kb downstream of the gene and has been shown to have the strongest association with body mass index and obesity risk in a number of populations." (PMID 32733386, 2020). "For example, The α-ketoglutarate–dependent dioxygenase (FTO) and melanocortin-4 receptor (MC4R) genes were confirmed to be obesity-associated loci, which promotes researchers to study the association of these variants with T2D." (PMID 33042976, 2020). "Heterozygous mutations in MC4R are the commonest cause of monogenic obesity, affecting approximately 0.1% of the population." (PMID 33231171, 2020). "The results of this study showed that the rs17782313 variant near MC4R was associated with hypertension, obesity, and high plasma levels of ghrelin and visfatin in a cohort of Arabic participants." (PMID 32733386, 2020). "Whereas chow-fed Mc4r-/- mice were shown to develop late onset obesity, hyperphagia, and simple steatosis due to genetic mutation, feeding a HFD induced ballooning degeneration, hepatic inflammation, and pericellular fibrosis." (PMID 32046285, 2020). "Mutations in MC4R, although rare (<1% of the population), represent the commonest cause of extreme early onset obesity." (PMID 32692746, 2020). "A previous study has demonstrated that the three MC4R (rs17782313, rs12970134 and rs476828) SNPs have an impact on obesity, but their relationship to the risk of obesity has yet to be clearly outlined." (PMID 32770936, 2020). "In these normal-weight carriers, the obesity-increasing effects of the MC4R mutations are offset through—at least in part—a significantly lower polygenic risk compared with the carriers with obesity." (PMID 32692746, 2020). "A number of obesity-associated genes have been identified in adipogenesis regulation, such as melanocortin-4 receptor (MC4R), uncoupling protein-1 (UCP1), and pro-opiomelanocortin (POMC)." (PMID 33425901, 2020). "Human genetic studies also revealed that 5.8% of subjects with severe obesity commencing at childhood have mutations in MC4R, demonstrating dysfunction of MC4R to be the most common cause of monogenic obesity." (PMID 33076233, 2020). "We focused our subsequent analyses on 11 MC4R mutations that did have an impact on obesity in the approximately 450,000 UK Biobank individuals of European ancestry." (PMID 32692746, 2020).
Obesity (continued). "We have identified a rare potentially pathogenic MC4R variant in a Brazilian patient with severe and adulthood-onset obesity." (PMID 33362866, 2020). "Although the Melanocortin-4 Receptor (MC4R) gene rs17782313 C/T has been consistently related to obesity risk, the interaction between MC4R polymorphism and diet quality indices on cardio-metabolic risk factors has not yet investigated." (PMID 32019489, 2020). "In adults, a systematic review showed that the interaction between the melanocortin 4 receptor (MC4R) gene (a protein-coding gene previously associated to BMI) and MD modulates the development of obesity and type 2 diabetes mellitus (T2DM) phenotypes." (PMID 33339255, 2020). "MC4R is also a centrally acting gene known to be the most common cause of monogenic obesity in extreme childhood obesity." (PMID 33193685, 2020). "The increase in ghrelin levels was expected since this variant is associated with obesity and probably affects the functionality of MC4R which is known to regulate appetite." (PMID 32733386, 2020). "Pathogenic variants in MC4R were the most frequently identified genetic cause of obesity in our cohort (9/282 patients, 3.2%)." (PMID 32384097, 2020). "MC4R mutations, both in dominant and in recessive forms, are the most common cause of monogenic obesity known so far." (PMID 33261141, 2020). "They had severe obesity, intractable hyperphagia and accelerated growth which is typical for MC4R deficiency." (PMID 30991789, 2019). "Next, we identified 58 individuals with rare pathogenic MC4R variants, 44 16p11.2 deletions, and 50 16p11.2 duplications that cause familial or de novo forms of obesity or leanness." (PMID 31653860, 2019). "Two polymorphisms in the MC4R (Val103Ileu and Ile251Leu) had been demonstrated to reduce the risk of obesity." (PMID 31035493, 2019). "Due to the critical role of MC4R in obesity pathology, the association between different SNPs of the MC4R gene and BMI and obesity in PCOS patients were demonstrated." (PMID 32133054, 2019). "We found that LoF variants in MC4R were associated with higher BMI and higher odds of obesity, severe obesity, type 2 diabetes, and coronary artery disease." (PMID 31002796, 2019). "Previously, a wide variability (ranging from 0.5 to 5.8%) in the frequency of MC4R mutations had been described in children and adolescents with obesity in different populations." (PMID 31035493, 2019). "For example, mutations in MC4R lead to the most prevelant form of monogenic obesity and, because the clinical features resemble those found in exogenous obesity, differential diagnosis can only be confirmed by detection of genetic variants." (PMID 30991789, 2019). "This dual‐cassette vector mimics the body's natural feedback system to achieve autoregulation of the transgene and its efficacy has been examined in genetic models of obesity and diabetes such as db/db mice and melanocortin‐4 receptor (MC4R) deficient mice." (PMID 30585393, 2019). "In clinical studies of patients with obesity and type 2 diabetes mellitus, it was demonstrated that some of them had the impaired hypothalamic MC4R-signaling and the inactivating mutations within the Mc4r gene." (PMID 30870482, 2019). "This receptor is a key protein in the hypothalamic regulation of food intake and energy expenditure and naturally-occurring inactivating MC4R variants are the most frequent cause of monogenic obesity." (PMID 31417496, 2019). "The MC4R gene mutations are one of the most common form of monogenic obesity, however the functional effects of polymorphic variants in general population remain uncertain." (PMID 30945034, 2019). "Mutations in melanocortin-4-receptor (MC4R) gene are one of the most common cause of monogenic obesity, however, the functional effects of polymorphic variants near MC4R gene in general populations remain uncertain." (PMID 30945034, 2019). "According to the evidence, the MC4R gene via a causal effect on obesity contributes to PCOS etiology." (PMID 32133054, 2019).
Obesity (continued). "An important research finding was reported regarding the role of MC4R gene polymorphisms on body weight control and fatness traits in livestock, as well as on early obesity in humans." (PMID 30634446, 2019). "They found that gain-of-function variants in the MC4R gene were associated with lower BMI and lower odds of obesity, type 2 diabetes, and coronary artery disease." (PMID 31686269, 2019). "Loss-of-function MC4R mutations are associated with early-onset severe obesity due to hyperphagia, hyperinsulinemia and increased linear growth." (PMID 30991789, 2019). "Earlier studies report a frameshift mutation in MC4R that reduces Gαs-mediated cyclic adenosine monophosphate accumulation is associated with dominantly inherited obesity in humans." (PMID 31686269, 2019). "In humans, mutations in MC4R are connected to early-onset obesity, and in mice, Mc4r knockout causes hyperphagic obesity." (PMID 31024451, 2019). "In this study, we examined MC4R variants’ (rs12970134 and rs17782313) contribution to obesity and their influence on the susceptibility to PCOS." (PMID 31429705, 2019). "To date, more than 166 mutations were reported in human MC4R locus, mainly associated with growth and obesity." (PMID 30634446, 2019). "Our present study first demonstrated that MC4R SNPs (rs2331841, rs6567160, rs17782313, rs571312, and rs12970134) are associated with obesity, especially for metabolic disorders in obese individuals." (PMID 31781208, 2019). "Melanocortin-4 receptor (MC4R) has been reported to be associated with the risk of obesity, and metabolically unhealthy obese (MUHO) patients tend to have a greater risk of cardiovascular complications than metabolically healthy obese (MHO) patients." (PMID 31781208, 2019). "Mutations in the MC4R gene were found at a frequency of approximately 3-4% in severe early-onset obesity, and the MC4R mutation is the most common monogenic cause of obesity, with a prevalence of 1.7–3.0% in obese individuals." (PMID 31781208, 2019). "A prospective cohort study is required to verify the association between MC4R polymorphisms and obesity and its related metabolic disorders." (PMID 31781208, 2019). "One of the most common single genes harboring variants associated with obesity is the melanocortin-4 receptor gene (MC4R)." (PMID 31035493, 2019). "Mutations in the melanocortine‐4 receptor (MC4R) gene are the most common cause of monogenic obesity, with a prevalence of 0.5%–5.8%, with the highest values expected in cohorts with early onset obesity." (PMID 31055886, 2019). "Melanocortin- 4 receptor (MC4R) deficiency is the most common monogenic form of obesity, affecting from 0.5% to 4% of obese children." (PMID 31344895, 2019). "In conclusion, this genetic study reveals that MC4R variants (rs12970134 and rs17782313) with genotypes A/A and C/C, respectively, were highly associated with obesity in PCOS." (PMID 31429705, 2019). "MC4R mutations are the most common genetic cause of monogenic obesity and also contribute in polygenic forms." (PMID 30991789, 2019). "The variant rs17782313 of MC4R is associated with obesity in both children and adults, regulating the control of energetic balance." (PMID 31350533, 2019). "These GWAS studies have detected variations in or near different genes, among them fat mass- and obesity-associated gene alpha-ketoglutarate dependent dioxygenase and melanocortin 4 receptor (MC4R) in obesity." (PMID 31429705, 2019). "While most MC4R variants caused loss of function, a subset caused gain of function; these variants were associated with significantly lower BMI and lower odds of obesity, type 2 diabetes, and coronary artery disease." (PMID 31002796, 2019). "We functionally characterized 61 MC4R variants identified in 0.5 million people from UK Biobank and examined their associations with body mass index (BMI) and obesity-related cardiometabolic diseases." (PMID 31002796, 2019).